ROS1 (ROS proto-oncogene 1, receptor tyrosine kinase)
Diseases named in the same sentence as ROS1 in open-access papers (continued):
Sharing a sentence is not in itself a finding about the gene and the disease.
cholangiocarcinoma (22 papers, 2011 to 2026). A carcinoma that arises from the intrahepatic biliary tree (intrahepatic cholangiocarcinoma) or from the junction, or adjacent to the junction, of the right and left hepatic ducts (hilar cholangiocarcinoma). "The purpose of this study was to gain further insight into the relationship and interplay between the expression of ALK, cMet, and ROS1 and the cytotoxicity of crizotinib, ceritinib, and capmatinib in cholangiocarcinoma cells." (PMID 38144528, 2023). "We aimed to investigate both protein expression and gene fusion of ROS1 in a larger number of patients with intrahepatic cholangiocarcinoma." (PMID 26475437, 2015). "Previous publications indicated that this shorter FIG clone fused to ROS1, expressed in cholangiocarcinoma, is highly proliferative and invasive." (PMID 24386191, 2013). "ROS1 expression was barely detectable, but high levels of ROS1 expression have been shown to be an indicator of better disease-free survival, indicating that the patient samples may be aggressive cholangiocarcinomas." (PMID 38144528, 2023). "The expression of ROS1 did not significantly correlate with known risk factors or etiologies of cholangiocarcinoma, or the adjuvant treatments." (PMID 26475437, 2015). "ROS1 protein expression was significantly correlated with well differentiated tumors, papillary or mucinous histology, oncocytic/hepatoid or intestinal type tumors, and periductal infiltrating or intraductal growing tumors (vs. mass-forming cholangiocarcinoma)." (PMID 26475437, 2015). "Indeed, cholangiocarcinoma with ROS1 gene fusion would be a good candidate for treatments targeting ROS1 such as crizotinib; however, the actual incidence and clinical significance of ROS1 rearrangements in BTC have not been fully known." (PMID 26475437, 2015). "ROS1 fusions have been examined in a variety of human malignancies, including NSCLC, cholangiocarcinoma and GBM." (PMID 40615663, 2025). "ROS proto-oncogene 1 (ROS1) rearrangements are identified in 1–2% of NSCLC and in several other malignancies such as cholangiocarcinoma (CCA), glioblastoma, or colorectal cancer." (PMID 33109256, 2020). "ROS1-GOPC fusions have been observed in anaplastic astrocytoma, NSCLC, ovarian serous tumor, cholangiocarcinoma, and acral lentiginous melanoma." (PMID 30719217, 2019). "ROS1 rearrangement was also found in other solid tumors such as non-small-cell lung cancer (NSCLC) and cholangiocarcinoma." (PMID 26366867, 2015). "In contrast, a significant portion of cholangiocarcinoma samples exhibited greater than moderate expression of ROS1, yet we could not find any ROS1 gene rearrangement by FISH." (PMID 26475437, 2015).
inflammatory myofibroblastic tumor (22 papers, 2015 to 2025). A multinodular intermediate fibroblastic neoplasm that arises from soft tissue or viscera, in children and young adults. "The discovery of ROS1 fusion rearrangements—most notably the TFG::ROS1 oncoprotein—has transformed our understanding of inflammatory myofibroblastic tumor (IMT) biology." (PMID 40868080, 2025). "Inflammatory myofibroblastic tumor fusions involving ROS1, PDGFRβ, RET, and NTRK have also been described in inflammatory myofibrosarcoma." (PMID 35865478, 2022). "Inflammatory myofibroblastic tumors are another rare malignancy that frequently harbor ALK or ROS1 translocations." (PMID 35233056, 2022). "Additionally, the detection of a TFG::ROS1 fusion in an ALK-negative inflammatory myofibroblastic tumor and the neoadjuvant use of crizotinib in that patient demonstrate the expanding relevance of targeted therapies in pediatric pulmonary malignancies." (PMID 40868080, 2025). "On the contrary, a variety of ROS1 re-arrangement or mutation were detected in various tumors, such as ROS1-EPHA7 fusion in breast cancer, ROS1-FN1 or ROS1-SLC12A2 re-arrangement in inflammatory myofibroblastic tumor, ROS1-WNK1 or ROS1-CD74 fusion or ROS1-G2032R mutation in lung cancer." (PMID 36998041, 2023). "In inflammatory myofibroblastic tumors, ROS1 expression predicts ROS1 gene rearrangement." (PMID 35140786, 2022). "In addition, ALK and ROS1 fusions are highly characteristic for inflammatory myofibroblastic tumors (IMT)." (PMID 30211169, 2018). "Other ROS1 fusion positive tumors that have been previously reported in the literature such as ROS1+ melanoma and ROS1+ soft tissue tumor (inflammatory myofibroblastic tumor [IMT]; were also identified in the database." (PMID 37853341, 2023). "Similarly, ALK/ROS1 inhibitors (crizotinib, ceritinib) demonstrate efficacy in inflammatory myofibroblastic tumors (IMTs), NSCLC, and renal cell carcinomas (RCCs) harboring TPM3‐ALK/ROS1 fusions." (PMID 41275415, 2025). "Inflammatory myofibroblastic tumor (IMT) is a very rare subtype of sarcoma, which frequently harbor chromosomal rearrangements, including anaplastic lymphoma kinase (ALK) rearrangements (almost 50% of the IMTs) and other kinase fusions such as ROS1." (PMID 34211840, 2021). "Based on the morphological, immunohistochemical, molecular findings and the good response to receptor tyrosine kinases inhibitors, the final diagnosis of the inflammatory myofibroblastic tumor with a previously undescribed ROS1 fusion is made, although ALK rearrangement is negative." (PMID 37735390, 2023).
melanoma (22 papers, 2013 to 2025). A malignant, usually aggressive tumor composed of atypical, neoplastic melanocytes. "In melanoma, both ROS1 mutations and ROS1 fusions have been reported, though their prevalence and implications differ." (PMID 40508177, 2025). "Despite these promising findings, further investigation is warranted to elucidate the precise role of ROS1 mutations and fusions in melanoma." (PMID 40508177, 2025). "This is thought to be associated with a significantly higher tumor mutational burden (TMB) in ROS1-mutated melanomas, potentially enhancing neoantigen presentation and immune system activation." (PMID 40508177, 2025). "Overall, patients with melanoma harbored a predominant prevalence of ROS1 mutation, with proportions of 25.0 and 14.8% respectively in the TCGA and the MSK datasets." (PMID 34221982, 2021). "We sought to elucidate the predictive effect of ROS1 mutation for immune checkpoint inhibitor (ICI) therapy in melanoma." (PMID 34221982, 2021). "The differences were further assessed by univariate logistic regression, and, after adjustment, only the mutations in NF1 and ROS1 remained independently associated with the CSD melanomas." (PMID 34680367, 2021). "Given the high prevalence of ROS1 mutation in melanoma, we first explored its predictive value for risk stratification of melanoma patients received ICI treatment in the MSK dataset." (PMID 34221982, 2021). "Precisely, ROS1 mutation in non-protein tyrosine kinase (PTK) domain but not PTK mutation was responsible for the immunotherapy-specific responses of the ROS1 mutated patients in melanoma." (PMID 34221982, 2021). "In parallel, ROS1 mutation was associated with higher TMB relative to the wild-type counterpart in the melanoma population (all P <0.001)." (PMID 34221982, 2021). "Overall, melanoma accounted for the highest proportion of ROS1 mutation (~20%) which made up the majority (~95%) of the ROS1-alterated cases." (PMID 34221982, 2021). "Melanoma accounted for the highest proportion of ROS1 mutation which made up the majority of the ROS1-alterated cases." (PMID 34221982, 2021). "In this genetic association study, we demonstrated a relatively high mutation frequency of ROS1 in pan-cancer especially melanoma." (PMID 34221982, 2021). "Emerging evidence suggests that melanomas harboring ROS1 mutations may exhibit heightened sensitivity to immune checkpoint inhibitors (ICIs), including PD-1 and CTLA-4 inhibitors." (PMID 40508177, 2025). "Furthermore, we performed GSEA to explain, from the perspective of transcriptomics, the immunotherapy-specific responses of ROS1 mutation versus wild-type using the RNA sequencing data of the TCGA melanoma dataset." (PMID 34221982, 2021). "Notably, ROS1 mutation accounted for the majority of the ROS1-alterated melanoma cases in both datasets (TCGA: 94.6%; MSK: 94.7%)." (PMID 34221982, 2021). "Moreover, external validation of the predictive significance of ROS1 mutation was conducted in two independent ICI-treated melanoma cohorts." (PMID 34221982, 2021). "ROS1 mutations are more frequently observed, occurring in approximately 14.8% to 25.0% of cases, while ROS1 fusions are rare and detected in only around 1% of melanomas." (PMID 40508177, 2025). "In melanoma, recent clinical trials have shown that the pan-Trk inhibitor entrectinib is has a therapeutic impact in Trk-fusion melanoma, but the mechanism is uncertain as entrectinib can also inhibit other signaling molecules, such as ROS-1 or ALK." (PMID 35457078, 2022). "It is noteworthy that non-PTK mutation of ROS1 yielded significantly prolonged OS relative to both ROS1 PTK mutation and wild type in the MSK ICI-treated melanoma population (P = 0.017)." (PMID 34221982, 2021). "We found that the nevogenic melanomas were associated with mutations in BRAF, while the CSD melanomas were associated with mutations in NF1, ROS1, GNA11, and RAC1." (PMID 34680367, 2021).
melanoma (continued). "The CSD melanomas, in contrast, showed mutations in a diverse group of genes that included NF1, ROS1, GNA11, and RAC1." (PMID 34680367, 2021). "Of interest, one case report demonstrated the efficacy of entrectinib in a patient with an acral melanoma harboring ROS1 gene fusion." (PMID 34831002, 2021). "An ongoing trial is currently recruiting patients to evaluate the use of entrectinib, a potent inhibitor of the tyrosine kinases ALK, TRKA/B/C, and ROS1, for the treatment of solid tumors, including melanoma (ClinicalTrials.gov identifier NCT02568267)." (PMID 28895885, 2017). "Similarly to ROS1 gene fusions, Neutrophic tropomyosin receptor kinase (NTRK) alterations in melanoma encompass both gene fusions and somatic mutations." (PMID 40508177, 2025). "In conclusion, we for the first time reveal the positive predictive value of ROS1 mutation, characterized with increased tumor antigenicity and gene damage, for ICI therapy in melanoma, which is distinct from the well-established role of ROS1 rearrangement for targeted therapy in NSCLC." (PMID 34221982, 2021). "Several prominent genes mutated in CSD melanomas included NF1, ROS1, GNA11, and RAC1." (PMID 34680367, 2021). "Therefore, the purpose of our study was to explore the predictive value of ROS1 mutation, instead of rearrangement, for the efficacy of ICI treatment in melanoma." (PMID 34221982, 2021). "In contrast, the CSD melanomas had a higher frequency of mutations than the nevogenic melanomas in NF1 (14/37, 37.8% vs. 6/82, 7.3%; p < 0.001), ROS1 (10/37, 27.0% vs. 4/82, 4.9%; p = 0.001), GNA11 (4/37, 10.8% vs. 1/82, 1.2%; p = 0.032), and RAC1 (6/37, 16.2% vs. 1/82, 1.2%; p = 0.004)." (PMID 34680367, 2021). "The non-PTK domain was the specific site of ROS1 mutation that determine the favorable responses to immune checkpoint therapy in melanoma." (PMID 34221982, 2021). "ROS1 mutation served as a favorable predictor for immune checkpoint therapy but not a prognostic factor in melanoma." (PMID 34221982, 2021). "Approximately, non-PTK mutation accounted for ~75% of ROS1 mutation in melanoma patients, namely 79.0% (n = 49) in the MSK ICI-treated melanoma population and 75.0% (n = 15) in the MEL-IPI cohort." (PMID 34221982, 2021). "Similarly, entrectinib has shown potential efficacy in ROS1 fusion-positive melanomas, suggesting that ROS1 fusion-directed therapies could be a viable treatment strategy in select cases." (PMID 40508177, 2025). "On the other hand, ROS1 fusions in melanoma may represent a therapeutic target akin to NSCLC." (PMID 40508177, 2025). "Furthermore, we identified the non-PTK domain as the specific sites of ROS1 mutation that determine the favorable responses to ICI therapy in melanoma." (PMID 34221982, 2021). "Moreover, FGFR3-TACC3 and ROS1-GOPC fusions were reported in melanoma." (PMID 32493317, 2020). "PAX3, a transcription factor involved in melanocyte development, the receptor tyrosine kinase KIT, CDKN1C, and EPHA5 were upregulated in the melanoma compared to the atypical nevus, while NTRK3 and ROS1 were downregulated in the same comparison." (PMID 35052351, 2021). "Among the protein kinase activation pathways, the expression levels of ROS1 and NTRK3 are only upregulated in the atypical tumor compared to the nevus and melanoma." (PMID 35052351, 2021). "Fusions previously identified in melanoma were detected in two patients (TACC3-FGFR3 and ROS1-GOPC fusion)." (PMID 32493317, 2020). "Increasingly, gene fusions involving various kinases, including ALK, ROS1, BRAF, RAF1, NTRK1, and NTRK3 have been identified within melanomas, and these fusion-positive melanomas often display spitzoid morphology." (PMID 32483240, 2020). "Fusions previously identified in melanoma were detected in two patients (TACC3-FGFR3 and ROS1-GOPC fusions)." (PMID 32493317, 2020). "Rearrangements in several genes, including BRAF, RET, ROS1, ALK, NTRK1, and NTRK3, have been characterized in subsets of melanoma." (PMID 32123303, 2020).
melanoma (continued). "Retrospective studies of spitzoid neoplasms have found activating fusions involving BRAF, RET, ROS1, ALK, or NTRK1 in 39% of melanomas with spitzoid morphology and just over 50% of Spitz nevi and atypical Spitz tumors." (PMID 32123303, 2020). "RAF1 fusion was detected in 4 cases (GC, melanoma, STS, and pancreatic cancer), BRAF fusion in 2 cases (BTC and STS), ALK fusion in 2 cases (CRC and BTC), ROS1 fusion in 1 case (CRC), and EGFR fusion in 1 case (CRC) with diverse counterparts." (PMID 32411236, 2020). "Collectively, ROS1 mutation, specifically the non-PTK mutation, is a potential predictor of ICI therapy in melanoma, which is distinct from the well-established role of ROS1 rearrangement for targeted therapy in NSCLC." (PMID 34221982, 2021). "Moreover, in vitro studies have shown that several genes are linked to melanomagenesis in the co-deleted region, including ARID1B, CCNC, and ROS1, although none have yet been shown to be functionally important in melanoma in vivo." (PMID 34140478, 2021). "TCGA analysis detected fusions in BRAF and RAF1 kinases in melanomas, but did not report fusions in ALK, ROS1, MET, RET, or NTRK, which are clinically targetable." (PMID 34831002, 2021). "In contrast to Spitz tumors with fusions of ALK, NTRK1, and ROS1, which are usually compound with a prominent epidermal component, epidermal involvement in the RAF1-fused melanomas was typically limited or absent." (PMID 32123303, 2020).
metastatic disease (16 papers, 2016 to 2026). "ROS1-rearranged adenocarcinomas are more likely to be associated with younger age and distribution of metastatic disease, including pericardial and nodal metastases." (PMID 33005033, 2020). "About 1–2% of NSCLC patients were found to have ROS1 rearrangement and up to 40% of patients with ROS1-positive metastatic disease presented with BMs." (PMID 39685828, 2024). "Treatment for metastatic disease included chemotherapy (pemetrexed-platinum), ROS1 TKI, chemo-immunotherapy and others." (PMID 38425761, 2024). "A tendency to defer ROS1-fusion testing until onset of late stage advanced or metastatic disease, often on an ad hoc basis after ruling out other oncogenic drivers such as EGFR and ALK, adds another layer of clinical heterogeneity." (PMID 35323360, 2022). "The ROS1 inhibitor entrectinib was developed to properly penetrate the BBB and remain in the central nervous system as a form of prevention and treatment of metastatic tumors in patients with locally advanced or metastatic ROS1-positive NSCLC." (PMID 33182254, 2020). "Up to 36% of patients with ROS1-positive NSCLCs have a BM at the diagnosis of metastatic disease." (PMID 35258806, 2022). "Forty-nine ROS1-expressing NSCLC patients, diagnosed with advanced metastatic disease, were included." (PMID 39195309, 2024). "For patients with metastatic disease, the outcome largely depends on the identification of a targetable driver such as EGFR, ALK, ROS1, ERBB2, BRAF, MET and more recently KRAS, RET, NRG1 and NTRK1-2-3, as mutations or gene fusions are highly predictive of response to matched targeted therapy." (PMID 35326552, 2022).
colorectal cancer (14 papers, 2018 to 2025). A primary or metastatic malignant neoplasm that affects the colon or rectum. "All these kinases displayed mutations in more than 6% of CDX2-suppressed colorectal cancers in the TCGA cohort, and some receptor tyrosine kinases, including EGFR, ERBB3, ERBB4, RET, ROS1, and ALK, showed even higher mutation rates in these cancers." (PMID 39452477, 2024). "Crizotinib has been proven to have a significant response and clinical benefit in patients with ROS1 genomic rearrangements or ALK fusion-positive colorectal cancer." (PMID 36672336, 2023).
gastric cancer (13 papers, 2009 to 2024). A primary or metastatic malignant neoplasm involving the stomach. "The SLC34A2 (4p15)-ROS1 (6q22) fusion is present in 0.4% of gastric cancer and is associated with ROS1 protein overexpression." (PMID 30361512, 2018). "ROS1-rearranged tumors are found in multiple types of human cancer, including NSCLC, gastric cancer, colon cancer, and spitzoid tumors, and ubiquitous ROS1 partner genes have been identified thus far." (PMID 31906059, 2019). "ROS1 rearrangement was also found in gastric cancer patients where IHC analysis revealed 23 (4.6%) positive cases among which 3 (0.6%) were FISH positive." (PMID 26366867, 2015). "Ectopic expression of this receptor tyrosine kinase Ros1 has been reported in many tumors of the central nervous system and recently in lung and stomach cancers as well." (PMID 19529782, 2009). "We previously reported the presence of a very rare ROS1 rearrangement in gastric cancer (GC) with an incidence of 0.8% using immunohistochemistry (IHC) screening." (PMID 26472021, 2015). "Regarding gastric cancer, our cohort yielded high-priority target recommendations for targeted therapy, such as MSI, Her2 expression, and PD-L1, while also uncovering rare but promising alterations such as ROS1 fusion and MET-amplifications." (PMID 36572733, 2023).
lung squamous cell carcinoma (13 papers, 2017 to 2026). "Lung squamous cell carcinoma had much less mutations as compared with LUAD, however some genes including e.g. KDR and ROS1 were frequently mutated in LUSC." (PMID 33888829, 2021). "Our findings suggest that clinicians should pay more attention toward the occurrence of ROS1 rearrangements and the application of crizotinib for lung squamous cell carcinoma treatment." (PMID 34235088, 2021). "However, a rare case of lung squamous cell carcinoma with a ROS1 rearrangement showed marked sensitivity to crizotinib." (PMID 40502411, 2025). "However, the incidence of driver mutations in squamous cell lung cancers is extremely low, therefore EGFR/ALK/ROS1 mutations should have no impact on the findings reported for the stratified analysis on squamous cell lung cancer." (PMID 35045806, 2022).
ovarian carcinoma (11 papers, 2011 to 2025). A malignant neoplasm originating from the surface ovarian epithelium. "Somatic mutations in ROS1 were the most frequently represented in this small case group, but their significance in breast and ovarian cancer is unknown at this time." (PMID 31346352, 2019). "Although each alteration is infrequent, ROS1 fusions with many kinds of 5′ partner genes (CCDC6, CD74, EZR, KDELR2, LRIG3, SDC4, SLC34A2 and TPM3) have been reported in lung, brain, biliary tract, and ovarian cancers." (PMID 23418494, 2013). "Finally, variants in the genes ROS1, NOTCH1, ALK, KMT2D, and SPOP have to our knowledge not previously been reported in ovarian cancer." (PMID 28611940, 2017).